TGFB3 (transforming growth factor beta 3)
Diseases named in the same sentence as TGFB3 in open-access papers (continued):
Sharing a sentence is not in itself a finding about the gene and the disease.
tumor (continued). "At the study endpoint, palbociclib treatment combined with increased TGFB3 expression greatly reduced tumor volume compared to that in control mice (lentiSAMv2) treated with palbociclib." (PMID 38831405, 2024). "Our study defines TGFβ3 as an actionable determinant of palbociclib sensitivity that potentiates its anti-tumor effects." (PMID 38831405, 2024). "We found that the anti-tumor effects of palbociclib were potentiated in TGFB3-overexpressing tumors, highlighting the value of TGFB3 in predicting palbociclib response in TNBC." (PMID 38831405, 2024). "Inside the tumor tissue, the three established isoforms of TGFβ, namely, TGFβ1, TGFβ2, and TGFβ3, are released by cancer cells or CAFs." (PMID 38111465, 2023). "The inflammatory cytokine IFNγ (Ifng), assigned a pleiothropic role in tumor immunity, was also reduced in Vegfr2Y1173F/+ tumors, whereas the levels of Tgfb3 and Tnfa remained unaffected." (PMID 37651195, 2023). "The presence of CAFs within the tumor, quantitatively depicted as FAP positivity, was strongly linked to the expression of MMP13, AKT1, TGFB3 and TGFBR2, among other factors." (PMID 35311102, 2022). "TGFβ1, TGFβ2, and TGFβ3 protein expressions were distributed in similar regions, with higher levels in the cell cytoplasm, and a small amount in the tumor stroma." (PMID 36119489, 2022). "Together with our findings, it appears that non-lymphoid cells, in particular myeloid cells, are critical sources of TGFβ1 and TGFβ3 across different tumor types." (PMID 34789823, 2021). "In comparison to anti-TGFβ3 or 1D11 treatment, anti-PD-1 alone was able to produce a significant anti-tumor effect." (PMID 34789823, 2021). "In our model of established B16 tumors, PD-L1 expression significantly increased on tumor-infiltrating CD11b+ and CD11c+ cells as a result of TGFβ1 and TGFβ3 isoform-specific and pan-TGFβ inhibition." (PMID 34789823, 2021). "At day 15 post tumor implantation, TGFβ1 and TGFβ3 are highly expressed on CD8+DCs and Ly6G+ granulocytes." (PMID 34789823, 2021). "Since we found that both TGFβ1 and TGFβ3 isoform expression were detectable at 11 days post tumor implantation, a time point at which the B16F10 tumors are palpable and well established, we began treatment with isoform-specific anti-TGFβ therapy at this time." (PMID 34789823, 2021). "Anti-TGFβ3 therapy resulted in the greatest delay in tumor growth (62.3% reduction in tumor size compared to control), followed by anti-TGFβ1 therapy (49.68%) and pan-TGFβ blockade (37.44%) calculated 24 days post tumor implantation." (PMID 34789823, 2021). "In B16 there is an equal expression of both isoforms on infiltrating immune cells and isoform-specific inhibition of either TGFβ1 or TGFβ3 curbed tumor growth." (PMID 34789823, 2021). "Single-cell transcriptional analysis of tumor cells revealed that several secreted factors involved in recruitment or chemotaxis of myeloid cells were increased, including Cxcl1, Cxcl2, Tgfβ3, and lactotransferrin (Ltf) after short-term Ab + Pal treatment." (PMID 31444334, 2019). "TGFB3 is a cytokine, with important roles in development, wound healing, the immune response and acts as a tumor suppresser in early cancers but can switch to promoting cancer progression in later stages." (PMID 31681438, 2019). "It binds isoforms of TGF-β (TGFB3 among them), which are tumour suppressors in the healthy intestinal epithelium, inhibiting cell proliferation and promoting apoptosis." (PMID 28740175, 2017). "Chemokines and cytokines including CCL2, CXCL12, CSF1, CCL5, CCL22, IL6 and TGFB3 are secreted by primary tumor cells to recruit immune cells to escape from anti-tumor immune responses." (PMID 28591712, 2017). "A similar adverse link was observed between RFS and the expression of TGFB2 and TGFB3 genes by tumor cells, with the latter representing one of the strongest indicators of a poor clinical outcome." (PMID 27215396, 2016).
tumor (continued). "It was also shown that TGFB3 mRNA had significantly the lowest expression in the Grade 3 tumours, which agreed with a few studies evaluating the mRNA and protein levels of TGFB3." (PMID 26703884, 2015). "High TGFB2, TGFB3 and TGFBR2 mRNA levels in tumours were generally associated with better prognosis for patients, especially those diagnosed with lymph node-negative diseases." (PMID 26703884, 2015). "Several genes that are implicated in angiogenesis (Vegfa, Hgf), suppression of immunity (Arg1, Tgfb3), and tumor invasion (Mmp2, Mmp14, Ctgf) were also highly expressed in our GAMs data set." (PMID 25658639, 2015). "Immunohistochemical staining of TGFβ1 and TGFβ3 in tumour tissues revealed their distinctive expression pattern." (PMID 12778073, 2003). "To determine whether RT induces the expression of TGF‐β and VEGF, we analyzed the transcription level of Tgfb1, Tgfb2, Tgfb3, and Vegfa using RNA‐seq data of irradiated versus non‐irradiated 4T1 tumor tissues." (PMID 40470716, 2025). "We also examined the TGFβ3/GLI2/YAP1 (the TGY signature) expressions in the tumor samples." (PMID 40027190, 2025). "Notably, the reduced Tgfb3 expression in macrophages further supports a shift toward a less immunosuppressive environment, given Tgf-β’s well-recognized role in promoting tumor growth and immune evasion." (PMID 41326332, 2025). "Additionally, we found that GLI2 expression significantly correlates with the level of tumor-infiltrating CAFs, second to TGFβ3, providing further support for targeting this signaling axis as a therapeutic target." (PMID 40027190, 2025). "We then showed that our top-ranking candidate gene, TGFB3, could synergize with palbociclib to generate strong anti-tumor effects both in vitro and in vivo." (PMID 38831405, 2024). "Using lower concentrations of palbociclib, while still achieving comparable or even stronger anti-tumor responses while TGFβ3 levels are elevated, could help prevent some of the associated on-target toxicity in patient." (PMID 38831405, 2024). "They indicate the ease with which TGFβ3 could be administered in the clinic in combination with palbociclib to achieve significant tumor growth inhibition using low doses of either treatment." (PMID 38831405, 2024). "However, of the mice treated with palbociclib, those with TGFB3-overexpressing tumors had significantly lower average tumor growth rates than the control mice." (PMID 38831405, 2024). "Similar results were obtained in an independent validation dataset of microarray-based mRNA levels for TGFB1, TGFB2, and TGFB3, and their correlated expression with specific transcription factors in tumor specimens from 41 pediatric patients with DIPG (n = 29) or H3K27M-mutant GBM." (PMID 36980562, 2023). "Similarly, a decrease in the expression of fibrosis hallmark gene markers tumor growth factor (TGFβ3) and connective tissue growth factor (CTGF) accompanied the decrease in cardiac fibrosis in the tumor-bearing mice." (PMID 37759510, 2023). "We obtained similar results in an independent validation dataset of microarray-based mRNA levels for TGFB1, TGFB2, and TGFB3, and their correlated expression with specific transcription factors in tumor specimens from 41 pediatric patients with DIPG (N = 29) or H3K27M-mutant GBM." (PMID 36980562, 2023). "HIF-1α promotes tumor metastasis to distant and more oxygenated tissues through the transcriptional activation of oncogenic growth factors such as transforming growth factor-beta 3 (TGF-β3) and epidermal growth factor." (PMID 38140111, 2023). "Epigenetic regulation of IGFL3 in UL through H3K27ac could lead to dysregulation of TGFβ3 pathway in this tumor." (PMID 35740301, 2022). "Since the CD45- population from isolated B16 tumors demonstrated lower protein expression of TGFβ1 and TGFβ3 compared to tumor-infiltrating Ly6C+ high monocytes, we focused on characterizing the isoform-specific expression of TGFβ on tumor-infiltrating lymphoid and myeloid immune cells." (PMID 34789823, 2021).
tumor (continued). "The major cell type expressing MMP9 mRNA and protein were tumor‐infiltrating neutrophils, while Tgfb1 mRNA expression was mostly restricted to tumor‐infiltrating monocytes and Tgfb2, and Tgfb3 mRNA expression was mostly restricted to tumor epithelium and stroma." (PMID 31793740, 2020). "TGFβ3 is known to act as a tumor promoter in triple-negative BCs." (PMID 29719590, 2018). "PTN (Pleiotrophin) could restrain the differentiation of epithelial cells in vivo and TGFB3 (Transforming growth factor-β 3) was shown to have tumor-suppressing function." (PMID 29190897, 2017). "Interestingly, positive correlations between the mRNA levels of TGFBR2 and the mRNA levels of TGFB1 (Spearman’s rho = 0.51, P = 5.6 × 10−5, P’ = 5.6 × 10−4) and TGFB3 (Spearman’s rho = 0.42, P = 0.0012, P’ = 0.012) were observed in the tumours (n = 59)." (PMID 26703884, 2015). "The up-regulated TGFB1 expression in malignant tumour cells and the up-regulated TGFB3 expression in premalignant tumour cells were very likely to have different, even opposite effects on the corresponding tumours, which also implicated the specific biology of different TGFβ isoforms." (PMID 26703884, 2015). "The mechanisms underlying the reduced TGFBR2 expression in tumours and the differentially regulated TGFB1 and TGFB3 expression by malignant and premalignant tumour cells may also have potential clinical implications that need to be further explored." (PMID 26703884, 2015). "Previous studies with Tgfb3 knockout mice reported normal cutaneous homeostasis in skin grafted on the back of nude mice, yet cell death was increased upon treatment with a tumor promoting agent." (PMID 23110169, 2012). "An explanation for the differences might be that Tgfb3 expression is correlated to different genetic changes occurring during tumor development/progression." (PMID 19426485, 2009). "Since TGFβ3 is involved in multiple cellular processes the effects of genetic variation on mRNA expression may vary during tumor progression due to interactions with other affected genes." (PMID 19426485, 2009). "However, TGFβ3 levels were increased in the two postoperative patients, an indication of possible relapse or tumour metastasis." (PMID 12778073, 2003). "Tumour cells produce TGFβ1 and TGFβ3 as shown in the current and previous studies." (PMID 12778073, 2003). "TGFβ3/GLI2/YAP1 expression was associated with anti-tumor immune desertion, as evident by a negative association with tumor-infiltrating lymphocytes, including the CD8 T cells, CD4 T cells, B cells, Th1, gamma delta T cells (γδ T cells), and T follicular helper cells (Tfh)." (PMID 40027190, 2025). "This is reflected in the mean palbociclib-mediated tumor growth inhibition in each group of mice at every timepoint investigated, where the palbociclib effect on tumor growth inhibition is significantly greater in TGFB3-overexpressing tumors as compared to control mice during the entire experiment." (PMID 38831405, 2024). "Consequently, the unique upregulation of TGF‐beta family genes TGFB1, TGFBR2, TGFBI, TGFB1I1, and TGFB3 in S‐ECM could be due to increased production of TGF‐beta by CAFs in the tumor microenvironment." (PMID 36637997, 2023). "While TGFβ1 is thought to be the primary isoform expressed in the immune system, our data suggest that TGFβ1 and TGFβ3 are both highly detectable in the tumor microenvironment and may play alternate roles in regulating T cell biology, thus offering alternate targets for anti-cancer therapy." (PMID 34789823, 2021). "Treating MSCs with recombinant TGFβ1 and TGFβ3 in the presence of FaDu CM led to significant inhibition of the observed phenotype at the cellular and molecular level, which further implicated TGFβ signaling in negatively regulating MSC differentiation in response to tumor CM." (PMID 24405819, 2013).
tumor (continued). "TGN can form a stable complex with TGFβ3, which contributes to the downregulation of the TGY signature, resulting in a significant reduction in tumor spheroid formation ability, cisplatin resistance, and CAF transformation potential." (PMID 41596251, 2026). "The authors attributed this increased TGFβ3 expression in myoFib-2 to its role in activating CAFs and CAF-mediated extracellular matrix remodeling and tumor progression." (PMID 40027190, 2025). "A tendency towards the upregulation of several known suppressors of anti-tumor immunity and initiators of epithelial-mesenchymal transition (EMT) was observed: TGFBR1, TGFBR2, TGFB3 and TPT1." (PMID 37033948, 2023). "TGFB1, TGFB3, NOG, and SMAD9, components of the TGF-β pathway, participate in tumor metastasis and cancer stem cells." (PMID 36344487, 2022). "The mean mRNA expression of TGFB3 (P = 0.0313), TIMP1 (P = 0.0469), GREM1 (P = 0.0156), and CTGF (P = 0.0313) were all increased in tumour stroma EVs compared to normal stroma EVs." (PMID 34596356, 2021). "Human OSA patients with high levels of TGFβ3 in tumour tissue have a shorter disease-free survival, whereas human patients with high grade OSA had significantly greater tumour expression of TGFβ1 when compared to low-grade OSA patients." (PMID 30477496, 2018). "We observed significant upregulation of CAF-derived TGFB3 in both the HCT116 (up 14-fold) and HT29 (up 8-fold) spheroid models, indicating a conserved mechanism that is agnostic to the genetic state of the tumor cells." (PMID 29245949, 2017). "Significantly higher TGFB1 and TGFB3 mRNA levels and lower TGFBR2 mRNA levels were observed in primary tumours compared with their paired normal tissues." (PMID 26703884, 2015). "The results indicate a reduced responsiveness of tumour cells to TGFβ, a preferential up-regulation of TGFB1 in malignant tumours and a preferential up-regulation of TGFB3 in premalignant tumours." (PMID 26703884, 2015). "This pathway includes well-known cancer-related genes such as FOS, TGFB3 and TGFB1 that increased connectivity in the tumor network." (PMID 25253512, 2014). "Immunostaining revealed that TGFβ1 was expressed in cancer cells but TGFβ3 in the stromal cells, whereas CD105 was exclusively expressed in vascular endothelial cells of tumour blood vessels." (PMID 12778073, 2003). "Additionally, genes typically involved with tumor growth and persistence were downregulated with the addition of ARG2i/COX2i/NOS2i to STING agonism (e.g., Ar, Tgfb3, Tead2, Pik3r2, Jun)." (PMID 38312842, 2024). "Notably, tumor samples from DIPG patients expressed significantly higher levels of TGFB2 mRNA than control pons samples, but the TGFB1, as well as TGFB3 mRNA levels in DIPG samples were significantly lower than in the control pons samples." (PMID 36980562, 2023). "Numerous cytokines and chemokines known to enhance stromal activity such as TGFB1, TGFB2, TGFB3, CXCL12, CCL2 and IL-6 were found downregulated in 211F MEF cells, suggesting a potential tumor-promoting function of Y211 phosphorylation through regulation of the secretome in the stromal environment." (PMID 35628489, 2022). "In CT26 isoform-specific inhibition with TGFβ1 and pan-TGFβ inhibition were effective at delaying tumor growth while TGFβ3 inhibition had no anti-tumor effect." (PMID 34789823, 2021). "Interestingly, our results reveal a down-regulation of TGFβ1 and an up-regulation of TGFβ2, TGFβ3, Smad4 and RAC1b in treated cells, suggesting that PRP treatment promotes the TGFβ pathway role via a tumour suppressive route." (PMID 31388092, 2019). "These CAFs express interleukin 6 (IL6), C-C motif chemokine 2 (CCL2), and Transforming Growth Factor Beta 3 (TGFB3) that induce the differentiation of peripheral blood mononuclear cell (PBMC) to MDSC, which contributes to T cell depletion in the tumor microenvironment." (PMID 31416205, 2019).
tumor (continued). "Thus, we propose that when FOXI3 in tumor cells modulate the secretion of other bone factors including SPOCK1, Dlx, MAF, PthrP, HAS2, SVEP1, TGFβ3, and FGF which further primes the microenvironment, creates a crosstalk to help tumors grow in the bone." (PMID 30018953, 2018). "TGFB3 mRNA expression was significantly lower in estrogen receptor-negative/progesterone receptor-negative/Basal-like/Grade 3 tumours." (PMID 26703884, 2015). "Indeed, TRPS1 and Cath-D co-repress transcription of secreted protein rich in cysteine gene (SPARC), a tumor suppressor in MDA-MB-231 ER− BCC and promote c-MYC and TGFB3 expression." (PMID 26183398, 2015). "However, such genes as IFI27 (−4.38), SLC22A7 (−3.97), IFIT1 (−3.91), TGFB3 (−3.71), and IFN-α induced (−3.72) also had stronger suppression at the transcript level in HCC-R tumor tissues." (PMID 24377043, 2013). "In addition, to our knowledge, there are no reports of increased expression of TGFβ3 in acidic tumor environments." (PMID 39992949, 2025). "Notably, TGFB1, TGFB2, TGFB3, S100A8, S100A9, IL6, and PTGES secreted by PMN-MDSCs exhibit both protumorigenic and immunosuppressive properties, playing significant roles in promoting tumor growth and evading immune responses." (PMID 41280721, 2025). "In the human PDAC patient tumor transcriptome (TCGA), we identify strong and significant correlations between tumoral GHR expression and known lymphangiogenic (LYVE1, FLT4, VEGFC, and PDPN) and angiogenic (PDGFRa, FGFR1, TGFB3, TGFB1, TGFBR2, HIF1a, IL6, and IL1B) markers." (PMID 39000545, 2024). "Furthermore, TGFB3 has also been reported to exert a cancer-preventive effect in non-clinical models of tumor development as well as human subjects." (PMID 36980562, 2023). "Without ample ligand to inhibit in CT26, TGFβ3 inhibition is unable to suppress tumor growth." (PMID 34789823, 2021). "To answer the question whether in our particular (non-responder) tumor TGFB3 may also interfere with EMT, we took a closer look into the expression of TGFB-related transcripts in both tumors." (PMID 28594404, 2017). "We showed that TGFβ2 expression but not TGFβ1 or TGFβ3 expression is preferentially elevated TNBC cell lines, patient serum and tumour samples." (PMID 38299307, 2024). "As a result, SHC1-OE-ASM treated with TGFB3 showed significantly elevated tumor cell migration rates, whereas OE-Ctrl-ASM showed no significantly changes in tumor cell migration rates after treated with TGFB3." (PMID 38360860, 2024). "Interestingly, the addition of anti-CTLA-4 with either TGFβ1 or TGFβ3 inhibition, but not pan-TGFβ inhibition, had an even stronger effect in prolonging overall survival compared to isoform-specific TGFβ blockade alone but did not significantly affect tumor growth." (PMID 34789823, 2021). "Interestingly, TGFB3 and IL6 exhibited a strong correlation in tumor tissues but not normal tissues." (PMID 40650134, 2025). "Similarly, TGFB3’s expression may be elevated in PDAC, but its role may not independently drive aggressive tumor biology to the extent that TGFB2 does." (PMID 40650134, 2025).